SESN2 (sestrin 2)
Diseases named in the same sentence as SESN2 in open-access papers (continued):
Sharing a sentence is not in itself a finding about the gene and the disease.
cancer (continued). "Sestrin 2 expression is upregulated under ER stress in cancer cells through the regulation of the activating transcription factor 4, inositol-requiring enzyme 1/X-box binding protein 1, and protein kinase RNA-like endoplasmic reticulum kinase signaling pathways." (PMID 34784907, 2021). "Changes in sestrin 2 expression have been observed in numerous cancer tissues and cell lines and play a significant role in cell proliferation, invasion, metastasis, apoptosis, autophagy, anoikis resistance, drug resistance, oxidative stress, and endoplasmic reticulum (ER) stress." (PMID 34784907, 2021). "Sestrin 2 appears to be a novel prognostic marker for cancers." (PMID 34784907, 2021). "Recent research indicated that SESN2 plays a crucial role in many kinds of cancer cells." (PMID 33942488, 2021). "We speculated that the dual effects of SESN2 in cancer regulation were related to its mediated autophagy." (PMID 33942488, 2021). "Alterations in sestrin 2 expression have been found in a majority of cancers." (PMID 34784907, 2021). "However, to a certain extent, this conclusion is not satisfactory because of the lack of more favorable experimental evidence and the role of sestrin 2 in cancer requires further validation." (PMID 34784907, 2021). "However, SESN2, as a ROS inhibitor, can play a vital role in maintaining the viability of cancer cells." (PMID 33942488, 2021). "In view of the dual role of SESN2 in cancer, further long‐term studies are required." (PMID 33942488, 2021). "In this review, we summarized the dual roles and mechanisms of sestrin 2 in various cancers." (PMID 34784907, 2021). "In addition, SESN2 plays a crucial role in cancer, metabolic disorders, cardiovascular diseases and neurodegenerative disorders." (PMID 33942488, 2021). "In addition to its critical roles in the homeostasis of cellular metabolism, SESN2 plays an important role in modulating survival and proliferation of cancer cells." (PMID 32155890, 2020). "However, lentiviral overexpression of SESN2 and mTOR inhibitors suppressed cancer cell proliferation, migration, and epithelial–mesenchymal transition." (PMID 32899752, 2020). "Further, to investigate this association, we evaluated the correlation between SESN2 and mTOR pathway-related markers, including RPTOR, MTOR, and RHEB, by analyzing RNA expression data from cancer patients using the Gene Expression Profiling Interactive Analysis (GEPIA) database." (PMID 32899752, 2020). "Moreover, accumulating evidence suggested that SESN2 played a crucial role in regulating cell proliferation, apoptosis and autophagy in various cancers." (PMID 32363721, 2020). "Inactivation of SESN2 notably decreases the basal respiration rate, the maximal respiration rate, and the respiration rate associated with ATP production in A549 cells indicating the important role of SESN2 in support mitochondrial activity in cancer and normal cells." (PMID 32287270, 2020). "The results might lead to a novel approach for radiotherapy or chemotherapy in cancers through the regulation of Sesn2 activity." (PMID 32010489, 2020). "As a ROS scavenger, Sesn2 can be activated in cancer cells to attenuate oxidative stress." (PMID 32010489, 2020). "Collectively, SESN2 has anticancer effects, and modulation of SESN2 expression might contribute to the treatment and prognosis of cancers." (PMID 31867002, 2019). "For example, SESN2 expression could be increased via the c-Jun N-terminal kinase (JNK) pathway to influence autophagy induction in cancer cells." (PMID 28118855, 2017). "In addition, SESN2 expression inhibits cancer growth while increasing the sensitivity of cancer cells to ionizing radiation." (PMID 28118855, 2017).
cancer (continued). "If so, low expression of SESN2 in NB cancers would be predicted to correlate with poor prognosis." (PMID 28783174, 2017). "Collectively, our findings indicated that Sesn2 may act as a tumor suppressor gene that can inhibit cancer cell proliferation viability through the regulation of Akt-mTOR-p70S6K signal pathway." (PMID 25962159, 2015). "However, as previously demonstrated, a specific type of stress, such as oxidative stress or DNA damage stimulates sestrin 2 transcription in cancer cells, and this induces the phosphorylation of AMPK through the interaction with AMPK." (PMID 24535669, 2014). "Interestingly, cancer cells first and primarily respond to nelfinavir and bortezomib with the upregulation of SESN2, the cell survival mechanism that could lead to alleviation of the oxidative stress." (PMID 37284849, 2023). "However, there are other investigations that indicate the inhibitory effects of SESN2 in cancer." (PMID 36611970, 2022). "Furthermore, SESN2 knockdown strongly reversed fisetin-induced apoptosis in cancer cells." (PMID 35527284, 2022). "Thus, this review aims to examine the literature regarding sestrin 2 in various cancers, summarize its roles in suppression and tumorigenesis, discuss potential mechanisms in the regulation of cancer, and provide a basis for follow-up research and potential cancer treatment development." (PMID 34784907, 2021). "Moreover, sestrin 2 function is different in several cancers." (PMID 34784907, 2021). "Thus, SESN2 has both anti‐proliferative and prosurvival effects in different cancer cells." (PMID 33942488, 2021). "Sestrin 2 may be a potential tumor suppressor in these types of cancer." (PMID 34784907, 2021). "However, Sesn2 is also important for maintaining the viability of cancers under several conditions." (PMID 32010489, 2020). "Given that SESN2 plays a pivotal role in the modulation of inflammasomes activation and tumor growth by gAcrp, elucidation of the molecular basis by which adiponectin induces SESN2 expression would provide a potential therapeutic target for the treatment of cancer." (PMID 32155890, 2020). "The SESN2/AMPK/mTOR pathway is essential for regulating cellular energy metabolism, stress response, and cancer progression." (PMID 40775338, 2025). "Among the cancer cell lines, PC3 and DU145 exhibited particularly reduced SESN2 expression, which led us to select these cell lines for experiments." (PMID 40661871, 2025). "In human papillary thyroid (B-CPAP) cancer cells subjected to 100 μM calycosin treatment, we see that activation of Sestrin2 (SESN2) and the subsequent up-regulation of p-AMPK and inhibition of p-mTOR, promoting cancer cell autophagy and apoptosis." (PMID 41463300, 2025). "Our previous data indicate that SESN2 supports cell death in response to genotoxic chemotherapeutic drugs, and inactivation of SESN1&2 in cancer cells potentially provides resistance to cell death induced by DNA damage." (PMID 39985075, 2025). "The 12 FRGs are divided into 4 categories according to their functions: lipid metabolism (GPX4, LPCAT3, ACSL5, ACSL6), antioxidant (CD44, SESN2, AIFM2), iron metabolism (CISD1, HSPB1), and cancer metabolism (SOCS1, FH, G3BP1)." (PMID 35559049, 2022).
cancer (continued). "Based on function, the 12 FRGs can be grouped into four classes: Lipid metabolism (GPX4, LPCAT3, ACSL5, and ACSL6), antioxidant metabolism (CD44, SESN2, and AIFM2), iron metabolism (CISD1 and HSPB1), and cancer metabolism (SOCS1, FH, and G3BP1)." (PMID 34784264, 2022). "It was pointed out that sestrin 2 (SESN2) is upregulated and protects cancer cells from oxidative stress-induced anoikis upon detachment of cells from ECM." (PMID 33435156, 2021). "Meanwhile, we also chose 5 random cancer-related genes for mRNA detection, and found that GADD45A, HBP1, and SESN2 were significantly up-regulated, whereas KIF20A and TOP2A were down-regulated, compared to the 0 h group (*P < 0.05)." (PMID 32850392, 2020). "Further investigation of this difference in the modulation of SESN2 expression by the Oxaliplatin and DHA combination is warranted, although the phenomenon may be associated with the unique genetic backgrounds of different cancer cell types and the variance in response to drugs." (PMID 31337142, 2019). "In cancer cells, c-Jun N-terminal kinase (JNK) pathway activation and its downstream factor c-Jun phosphorylation are required for the regulation of SESN2 transcription under serum deprivation." (PMID 31867002, 2019). "It is interesting that mTOR-stimulated SESN2 activation modulates PTEN, and both mutant PTEN and overactivated mTOR are commonly found in human cancers." (PMID 25792980, 2015). "Moreover, SESN2 knockdown weakened the tumor suppressor effect of FAM3D KO, but SESN2 overexpression reduced the cancer-promoting effect of FAM3D overexpression." (PMID 39388305, 2024). "The transcriptional activation of SESN2 is one of the negative feedback mechanisms for inhibiting chronic activation of mTORC1 and preventing the positive effects of mTORC1 on cancer cells proliferation and progression." (PMID 37284849, 2023). "Moreover, the cancer cells treated with nelfinavir showed reduced mTOR activity and increased ATF4-mediated SESN2 expression level." (PMID 37284849, 2023). "In contrast to our prediction, Sesn2 supports tumor growth and does not have any effect on life expectancy in the Kras-based cancer model." (PMID 31857853, 2019). "Interestingly, cancer cells treated with the nelfinavir showed reduced mTOR activity and increased ATF4 and SESN2 expression levels." (PMID 31546746, 2019). "Moreover, the authors speculate that SESN2-mediated suppression of HIF-1α accumulation and cancer cell migration could have resulted from AMPK activation." (PMID 37284849, 2023). "Consequently, the role of SESN2 in cancer prognosis and progression is not clear, particularly for chemo- and radioresistance." (PMID 36611970, 2022).
tumor (50 papers, 2012 to 2025). "In vivo studies are needed to further determinate the association between SESN2 and HCC pathology, including tumor size and number, tumor stage, survival rate, prognosis, etc., and testify the therapeutic implication of SESN2 modulation." (PMID 36841824, 2023). "The lower expression of SESN2 was associated with advanced tumour stage, lymph node and liver metastasis and vascular invasion." (PMID 37284849, 2023). "Some studies identified sestrin 2 as an oncogene, which caused accelerated tumor cell growth and migration and suppressed apoptosis." (PMID 34784907, 2021). "The genes encoding SESN1 and SESN2 proteins are potential candidates for tumor suppressors in the lung." (PMID 31857853, 2019). "Loss of SESN2 increased mTORC1 activation and correlated with bigger tumours in the context of CRC." (PMID 40361504, 2025). "Interestingly, low expression of SESN2 has been associated with advanced tumour stage, lymphatic invasion, metastasis, vascular invasion, liver metastasis and decreased survival rate." (PMID 37284849, 2023). "However, tumor cells develop various mechanisms to overcome cellular stress, for example by up-regulating SESN2 expression, which causes resistance to chemotherapeutics or radiation." (PMID 36611970, 2022). "While we observed that expression of SESN1 and SESN2 is often decreased in human tumors, inactivation of Sesn2 in mice positively regulates tumor growth through a mechanism associated with activation of AKT, while knockout of Sesn1 has no additional impact on carcinogenesis in Sesn2-deficient mice." (PMID 31857853, 2019). "In addition, SESN2 has been implicated as a tumour suppressor that can inhibit angiogenesis and promote autophagy, underscoring the importance of elucidating the molecular mechanism by which SESN2 regulates pathways of metabolism and suvival." (PMID 22363791, 2012). "The differential expression of Sesn2 in different tumor tissues and cell lines may be associated with the different activation mechanisms, and its differing effects may be associated with the activation states of several downstream signaling pathways regulated by it." (PMID 41614860, 2025). "Sesn2-deficient mouse embryonic fibroblasts were significantly more susceptible to oncogenic transformation than wild type counterparts, suggesting that Sesn2 may have tumor suppressive activity." (PMID 32010489, 2020). "Disabling SESN1 and/or SESN2 in A549 cells amplifies cell growth and bestows resistance to cell death under glucose scarcity, thereby fostering early tumor expansion." (PMID 39759146, 2024). "There is a correlation between the low expression of SESN2 and tumor progression and an unfavorable prognosis." (PMID 36980973, 2023). "We found that SESN2 knockdown significantly slowed tumour growth in response to chemotherapeutic agents; the tumour volume and weight are significantly decreased in the SESN2 shRNA + Cis group compared with those in the control shRNA + Cis group." (PMID 34646824, 2021). "Sestrin 2 was deemed a potential tumor suppressor that repressed cell proliferation, enhanced apoptosis, and induced autophagy." (PMID 34784907, 2021).
tumor (continued). "Activated sestrin 2 has been found to be beneficial for tumor cell survival under diverse stress conditions." (PMID 34784907, 2021). "Overall, sestrin 2 plays a crucial role in suppressing tumor growth by inhibiting cellular proliferation, migration, and invasion, and inducing apoptosis." (PMID 34784907, 2021). "Sestrin 2 was reported to participate in inhibiting tumor cell proliferation, migration, and invasion and inducing apoptosis." (PMID 34784907, 2021). "Sestrin 2 associated with AMPK to inhibit mTOR signaling and enhanced radiation therapy-induced tumor cell death." (PMID 34784907, 2021). "Sestrin 2 was reported to regulate various cellular processes, such as tumor cell proliferation, invasion and metastasis, apoptosis, anoikis resistance, and drug resistance." (PMID 34784907, 2021). "The SESN2 mRNA levels were significantly more increased in the tumor than in normal tissues in TCGA dataset (p < 0.05)." (PMID 32899752, 2020). "We have previously shown that SESN2 suppresses cell proliferation and stimulates cell death in tumor cells in response to DNA-damage and cytokines, however, it can also support cell viability under particular stress conditions in certain cell types." (PMID 31857853, 2019). "Inactivation of Sesn2 decreases the number of proliferating cells that potentially contributes to the retardation of tumor growth in the Sesn2-null mice." (PMID 31857853, 2019). "Contributions of sestrin 2 to regulation of the AMPK/mTORC1 signaling pathway during tumor progression, by affecting protein synthesis, cell growth, and proliferation, have been widely documented." (PMID 28525387, 2017). "In all, SESN2 exerts significant anti-oncogenic effects, and high SESN2 expression substantially suspends malignant behavior that facilitates tumor development." (PMID 28118855, 2017). "Our previous study in CRC patients found that sestrin 2 was downregulated in neoplastic tissues, and correlated with advanced tumor stage as well as lymphatic and vascular invasion." (PMID 28525387, 2017). "Tumor volume, monitored every week between days 14 and 42 after tumor cell implantation, decreased significantly over time in sestrin 2-overexpressing xenografts." (PMID 28525387, 2017). "SESN2 plays important roles in the regulation of cell survival, cell protection, and tumor suppression." (PMID 28118855, 2017). "Recently, one member of this family, SESN2, has received attention for acting as a tumor suppressor that can inhibit angiogenesis and promote apoptosis." (PMID 28118855, 2017). "SESN2, a tumor suppressor, functions as an intracellular leucine sensor that negatively regulates the TORC1 signaling pathway through the GATOR complex." (PMID 29296193, 2017). "Potential tumor-suppressing effects of sestrin 2 are thought to arise from its ROS detoxifying actions and its ability to regulate AMPK/mTOR signaling." (PMID 28525387, 2017). "In this study we identified up-regulation of SESN2 and SESN3 in intratumoral NK-92 cells, suggesting that the tumor microenvironment induced the expression of SESN2 and SESN3." (PMID 29163816, 2017). "Quantification of PCNA-, γ-H2AX- and TUNEL-positive cells showed that tumor cell proliferation is significantly increased in tumors isolated from Sesn2-/- mice, while DNA damage and apoptosis were not significantly altered by the loss of Sestrin2." (PMID 26913956, 2016). "Our shRNA-based screen has demonstrated Sesn2 is a potential tumor suppressor in lung epithelial cells." (PMID 25962159, 2015).